PTBP1 (polypyrimidine tract binding protein 1)
Description:
Plays a role in pre-mRNA splicing and in the regulation of alternative splicing events. Activates exon skipping of its own pre-mRNA during muscle cell differentiation. Binds to the polypyrimidine tract of introns. May promote RNA looping when bound to two separate polypyrimidine tracts in the same pre-mRNA. May promote the binding of U2 snRNP to pre-mRNA. Cooperates with RAVER1 to modulate switching between mutually exclusive exons during maturation of the TPM1 pre-mRNA. Represses the splicing of MAPT/Tau exon 10. Binds to polypyrimidine-rich controlling element (PCE) of CFTR and promotes exon skipping of CFTR exon 9, thereby antagonizing TIA1 and its role in exon inclusion of CFTR exon 9. Plays a role in the splicing of pyruvate kinase PKM by binding repressively to a polypyrimidine tract flanking PKM exon 9, inhibiting exon 9 inclusion and resulting in exon 10 inclusion and production of the PKM M2 isoform. In case of infection by picornaviruses, binds to the viral internal ribosome entry site (IRES) and stimulates the IRES-mediated translation.
Synonyms: PTB; HNRPI; HNRNP-I; PTB2; PTB3; PTB-1; PTB4; pPTB; HNRNPI; PTB-T; STADS
Tractability: Small molecule: it has a binding pocket of medium quality; it belongs to a druggable protein family. PROTAC: UniProt records ubiquitination sites on it; ubiquitination databases record sites on it; its protein half-life has been measured; a small molecule that binds it is known.
Target class: Other nuclear protein
Chemical probes: Metarrestin
Gene: Protein-coding gene on chromosome 19 (797,075 to 812,327, forward strand). Ensembl gene ENSG00000011304.
Subcellular location: Nucleus
Subcellular location (Human Protein Atlas): Nucleoplasm
Pathways (Reactome):
Metabolism of RNA: Processing of Capped Intron-Containing Pre-mRNA; mRNA Polyadenylation; mRNA Splicing - Major Pathway
Disease: Dengue Virus-Host Interactions
Signal Transduction: FGFR2 alternative splicing
Gene Ontology:
Molecular function: pre-mRNA binding; protein binding; RNA binding; poly-pyrimidine tract binding; nucleic acid binding
Biological process: IRES-dependent viral translational initiation; negative regulation of mRNA splicing, via spliceosome; negative regulation of muscle cell differentiation; negative regulation of RNA splicing; positive regulation of calcineurin-NFAT signaling cascade; regulation of alternative mRNA splicing, via spliceosome; mRNA processing; regulation of cell differentiation; RNA splicing; negative regulation of gene expression; negative regulation of mRNA metabolic process; negative regulation of neuron differentiation
Cellular component: cytoplasm; extracellular exosome; membrane; nucleolus; nucleoplasm; P-body; nucleus
Genetic constraint (gnomAD): Loss-of-function variants: 8 observed, 57.93 expected, observed/expected ratio (o/e) 0.14, 90% interval 0.08 to 0.25. The synonymous counts are far from expectation, so gnomAD's model fits this gene poorly and the ratio says little. Missense variants: 686 observed, 767.45 expected, observed/expected ratio (o/e) 0.89, 90% interval 0.84 to 0.95. Synonymous variants: 490 observed, 327.05 expected, observed/expected ratio (o/e) 1.5, 90% interval 1.39 to 1.61.
Homologues: Orthologues: macaque PTBP1 (99% identical), guinea pig PTBP1 (98% identical), chimpanzee PTBP1 (98% identical), mouse Ptbp1 (97% identical), pig PTBP1 (97% identical), rat Ptbp1 (97% identical), dog PTBP1 (94% identical), tropical clawed frog ptbp1 (86% identical), zebrafish ptbp1a (80% identical), zebrafish ptbp1b (77% identical), rat Ptbp1-ps3 (76% identical), Drosophila melanogaster heph (57% identical), and 1 more. Paralogues in human: PTBP3 (73% identical), PTBP2 (72% identical), HNRNPL (29% identical), HNRNPLL (26% identical), RBM20 (24% identical).
Diseases named in the same sentence as PTBP1 in open-access papers:
PTBP1 is named in the same sentence as 180 diseases in open-access papers, as found by Europe PMC text mining. Sharing a sentence is not in itself a finding about the gene and the disease. The quoted sentences say what the papers report.
breast carcinoma (58 papers, 2012 to 2025). "In breast cancer on aberrant splicing by protein–protein interaction analysis, PTBP1 was identified as a central gene associated with brain metastasis of breast cancer." (PMID 40579921, 2025). "Both ENOX1 and PTBP1 evinced the same trend as the ensemble of these RBPs, that is, their expression levels are positively correlated with those of the associated TCNEs as well as breast cancer development." (PMID 40427520, 2025). "In breast cancer, PTBP1 increases the expression of CDC42‐v1 isoform, which promotes the formation of filamentous pseudopods through variable splicing and improves tumour cells' migration and invasion ability." (PMID 40579921, 2025). "An increasing number of studies have shown that PTBP1‐mediated mRNA alterations have essential functions in tumours, including colorectal cancer, hepatocellular carcinoma, breast cancer, and oesophageal squamous cell carcinoma." (PMID 40579921, 2025). "They unveiled an interaction between Dio3os and polypyrimidine tract-binding protein 1 (PTBP1), a splicing suppressor that affects RNA processing and is linked to breast cancer cell proliferation and glycolysis." (PMID 41235096, 2025). "To validate the role of these factors in breast cancer models, we observed notable increases in both ex4:3 bp and ex4:22 bp isoforms following PTBP1 depletion." (PMID 41258078, 2025). "For instance, the functional ribonucleoprotein complex of UCA1 and PTBP1 promoted breast cancer growth by suppressing p27 mRNA level." (PMID 38273088, 2024). "PTBP1 has been proven to affect the behaviour of breast cancer and bladder cancer cells or interfere with autophagy in olfactory mucosa mesenchymal stem cells by regulating the PTEN/PI3K/AKT signalling pathway." (PMID 39422584, 2024). "Previous study has reported that lncRNA can regulate PTBP1 functions in breast cancer development, autophagy process and inflammation activation." (PMID 36635762, 2023). "Studies have also found that PTBP1 can participate in the EMT of breast cancer cells and can affect the occurrence, invasion, and metastasis of tumours." (PMID 38002944, 2023). "NR2F1-AS1 is also upregulated in dormant breast cancer stem-like cells and increases tumor dissemination by recruiting PTBP1 to the mRNA of its sense gene (NR2F1), promoting its translation so that NR2F1 represses ΔNp63 transcription." (PMID 37445988, 2023). "This discovery provides a theoretical basis for PTBP1 as a new molecular target for breast cancer treatment." (PMID 38002944, 2023). "Recently, PTBP1 was reported to promote breast cancer cell proliferation via autophagy and the PTEN/Akt pathway." (PMID 37392846, 2023). "Numerous studies have shown that PTBP1, a protein coding gene, played essential roles in various cancers, including colorectal cancer, renal cell cancer, breast cancer, and glioma." (PMID 36307882, 2022). "Screen of the glycolytic metabolites affected by DIO3OS and PTBP1 and further verification of the splicing events in glycolytic enzymes identified LDHA as a key downstream target of DIO3OS and PTBP1 in AI-resistant breast cancer cells." (PMID 36418319, 2022). "PTBP1 is known to play in various cancers, such as colorectal cancer, renal cell cancer, breast cancer, glioma and liver cancer." (PMID 35292107, 2022). "We also explored the molecular mechanism of the total protein and phosphoproteins of PTBP1 proteins in breast cancer, colon cancer, ovarian cancer, and UCEC using the CPTAC dataset." (PMID 36595978, 2022). "Together, DIO3OS regulates the aerobic glycolysis as well as proliferation in LTED breast cancer cells via PTBP1." (PMID 36418319, 2022). "For example, we found that retinoid acid (RA) was capable of increasing PTBP1 levels leading to reduction of FGFR1β/FGFR1α ratio in breast cancer cells." (PMID 30713601, 2019). "Knockdown of PTBP1 impairs tumor cell growth, colony formation, in vitro invasiveness of breast cancer cell lines and transformation state of HMECs." (PMID 31666932, 2019).
breast carcinoma (continued). "Based on these results, it seems that in breast cancer cells, the oncogenic function of MACC1-AS1 largely relies on coordinated association of MACC1-AS1 with PTBP1 and individual miRNAs." (PMID 31822653, 2019). "UCA1 interaction with PTBP1 had been described in breast cancer cells, where the interaction induced IRES-mediated translation initiation of p27 mRNA to promote cancer cell proliferation." (PMID 30349036, 2018). "In cancer, it has been reported that PTBP1 is over-expressed in glioblastoma, ovarian tumor tissues, and breast cancer cells." (PMID 26980745, 2016). "Our previous study showed that PTBP1 played a role in the tumorigenesis of ovarian and breast cancer and regulated cellular metabolism by controlling the alternative splicing of pyruvate kinase." (PMID 26336992, 2015). "PTBP1 was shown to play a role in maintaining the growth and malignant properties of breast cancer cells." (PMID 26498360, 2015). "Concordance of regulated mechanisms by PTBP1 across three cell lines (neuronal, breast cancer and ovarian cell lines) discovered by N-of-1-pathways." (PMID 25079003, 2014). "We employed several breast cancer lines to investigate if the effect of H2O2 on PTBP1 levels has a general nature." (PMID 22911749, 2012). "We further demonstrate that down-regulation of PTBP1 by H2O2 occurs at the protein level with variable regulation observed in different breast cancer cells." (PMID 22911749, 2012). "We observed that similar concentrations of H2O2-induced PTBP1 degradation in three out of four investigated breast cancer lines." (PMID 22911749, 2012). "To determine the generality of H2O2-induced PTBP1 degradation, we tested additional breast cancer lines, including: MDA-MD-453, MDA-MD-231 and MCF7." (PMID 22911749, 2012). "Furthermore, Dio3os interacts with polypyrimidine tract binding protein 1 (PTBP1) to facilitate a metabolic shift towards glycolysis in breast cancer cells, thereby promoting increased expression of lactate dehydrogenase A (LDHA)." (PMID 41235096, 2025). "However, previous studies have reported contrasting results, indicating that PTBP1 interference promoted autophagy in breast cancer, olfactory mucosa mesenchymal stem cells, and GC." (PMID 39153986, 2024). "Furthermore, increased levels of RRM containing proteins in cancer is illustrated by the overexpression of the splicing factors Polypyrimidine tract‐binding protein 1 (PTBP1) in glioma and hnRNP A2/B1 in breast cancer." (PMID 39668490, 2024). "Additionally, previous studies have reported the promotion of cancer metastasis by PTBP1 in colorectal cancer, hepatocellular carcinoma, and breast cancer." (PMID 38247832, 2024). "PTBP1 also promoted breast cancer cell proliferation by autophagy and the PTEN/Akt pathway." (PMID 37392846, 2023). "Studies have shown that PTBP1 in breast cancer and lung cancer cells can increase the metastatic power and invasion ability of breast cancer and lung cancer cells by affecting the assembly of F-actin and the formation of pseudopodia, and promote the occurrence of metastatic tumors." (PMID 37670313, 2023). "PTBP1 has also been reported to promote EMT progression in breast cancer and in gastric cancer." (PMID 36635762, 2023). "Cassette exons differentially spliced between high- and low-metastatic breast cancer cells showed enrichment for a number of RNA motifs, which could represent binding sites for RBPs involved in breast cancer malignancy, including PTBP1, SRSF1, and SRSF9." (PMID 33918758, 2021). "PTBP1 promoted breast cancer cell growth by regulating PTEN/Akt signaling and autophagy." (PMID 34716285, 2021). "We calculated the amount of each splicing factor and found that the HNRNPA2B1 level was slightly lower in breast cancer patients and all other splicing factor levels higher; this difference reached significance for PTBP1 (p < 0.05), HNRNPK_ex89 (p < 0.05) and SRSF6 (p < 0.01)." (PMID 32756364, 2020).
breast carcinoma (continued). "Furthermore, we demonstrate that H2O2-induced degradation of PTBP1 differs in various breast cancer cell lines." (PMID 22911749, 2012). "So far, no breast cancer-associated single nucleotide polymorphisms (SNPs) of PTBP1 have been reported, however, this finding may have implications for the role of PTBP1 SNP in endocrine therapies in cancers." (PMID 36418319, 2022). "Importantly, we found that several RBPs, which are able to recognize the enriched sequences at 5′ and 3′ splice-sites and inside the AS cassette exons, were differentially expressed in breast cancer and during breast tumor progression, including PTBP1, SRSF1, and SRSF9." (PMID 33918758, 2021). "Moreover, others have linked more splicing factors such as the hnRNPs, SRSF1, SRPK1, and PTBP1 to breast cancer migration and metastasis formation, making it very interesting to systematically evaluate the role of splicing in breast cancer cell migration in future studies." (PMID 31278301, 2019). "Other than PTBP1, another trans-splicing factor, serine/arginine-rich (SR) splicing factor 55 (SRp55), may also play a role in ER regulation of FGFR1β splicing in ER+ breast cancer cells." (PMID 30713601, 2019). "PTBP1 and NCAPG play a role in some cancers, including colorectal cancer, renal cell carcinoma, breast cancer, and glioma, and can regulate tumorigenesis, invasion, and migration." (PMID 41438761, 2025). "PTBP1 promotes the exclusion of exon 18a which results in the production of the pro-invasive TCF3-18B (E47) isoform which promotes EMT and invasion of breast cancer cells under hypoxia." (PMID 41150697, 2025). "The AS factor PTBP1 induces the transformation of pyruvate kinase M1 (PKM1) to M2 (PKM2) and promotes glycolysis in breast cancer cells by participating in the cleavage of pyruvate kinase precursor mRNA." (PMID 40702000, 2025). "Therefore, PTBP1 may be a new biomarker for breast cancer and a new target for therapy." (PMID 40579921, 2025). "In breast cancer cells, binding of lncRNA MACC1‐AS1 to PTBP1 reduces its own degradation and increases its sponge effect on multiple oncogenic miRNAs (miR‐145‐3p, miR‐384, or miR‐342‐5p) to promote cell proliferation and breast tumour progression." (PMID 40579921, 2025). "Nonetheless, PTBP1i was able to efficiently modulate splicing events known to be regulated by PTBP1, after transfection into MDA‐MB‐231 breast cancer cells, and inhibit proliferation and colony formation." (PMID 39668490, 2024). "The results of the CPTAC dataset showed higher expression of PTBP1 total protein in LUAD, COAD, ovarian cancer, clear cell renal cell carcinoma, breast cancer, and UCEC tissues than in normal tissues (P < .001)." (PMID 36595978, 2022). "Seven types of tumors (ovarian cancer, breast cancer, colon cancer, UCEC, and LUAD) were analyzed based on the CPTAC dataset to compare the phosphorylation levels of PTBP1 in tumor and normal tissues." (PMID 36595978, 2022). "For example, PTBP1 promotes the growth of cancer cells through the PTEN/Akt pathway and autophagy in breast cancer." (PMID 34869345, 2021). "Five out of the six splicing factors have been shown before to be overexpressed in breast cancer: HNRNPA1, HNRNPA2B1, HNRNPK, PTBP1 and SRSF6." (PMID 32756364, 2020). "Previously, PTBP1 was recognized as an oncogene in GBM and as having an onco-genetic function in breast cancer cell lines and ovarian tumors." (PMID 29695138, 2018). "In breast cancer, lncRNA ZNF649‐AS1 induced trastuzumab resistance by increasing the expression level of ATG5 by enhancing the stability of ATG5 mRNA through binding to PTBP1." (PMID 40579921, 2025). "In the clinical treatment of breast cancer, H3K27ac modification-induced upregulation of lncRNA ZNF649-AS1 gene may lead to autophagy and trastuzumab resistance by binding to PTBP1 and promoting ATG5 transcription." (PMID 36635500, 2023).
breast carcinoma (continued). "Therefore, DIO3OS specifically interacts with nuclear PTBP1, a splicing regulator that supports the growth and aerobic glycolysis of LTED breast cancer cells." (PMID 36418319, 2022). "Here, we demonstrate that lncRNA DIO3OS directly interacts with PTBP1 protein in the nucleus and further stabilizes the mRNA of LDHA by protecting the integrity of its 3’UTR, ultimately activates glycolytic metabolism in AI-resistant breast cancer cells." (PMID 36418319, 2022). "For example, the β-deletion has been shown or speculated to be regulated by RMB10 in pancreatic cancer; NOVA1/PTBP1 in lung cancer; SRSF11, hnRNPH2, and hnRNPL in breast cancer; and MCPH1/BRIT1 in ovarian cancer." (PMID 33924498, 2021). "Furthermore, we observed splicing changes of known PTBP1 targets, PKM233,35, RTN438, SNAP91, and PTBP239, when PTBP1i was introduced into breast cancer cells." (PMID 30962446, 2019). "Splice factors that are suggested to control the Warburg effect are multiplayers PTBP1, hnRNPA1 and hnRNPA2 which not surprisingly are also involved in breast cancer growth and invasion." (PMID 31666932, 2019). "Collectively, lncRNA DIO3OS directly interacts with PTBP1 protein in the nucleus and stabilizes the mRNA of LDHA by protecting the integrity of its 3’UTR, which consequently upregulates LDHA expression and activates glycolytic metabolism in AI-resistant breast cancer cells." (PMID 36418319, 2022). "As the expression of DIO3OS increases in breast cancer cells undergoing AI resistance, the aberrant activation of DIO3OS/PTBP1/LDHA glycolysis cascade may endow tumor cells with metabolic adaptation that allows them to survive from AI-caused estrogen deficiency." (PMID 36418319, 2022). "Thus, we can conclude that although the majority of breast cancer cell lines we tested (3 out of 4) responded to H2O2 treatment by down-regulation PTBP1 levels, the response is not universal." (PMID 22911749, 2012). "Knockdown of PTBP1 prevented SASP induction in response to doxorubicin in IMR90 cells, irradiation in human fibroblasts, and oncogenic HER2 expression in MCF7 breast cancer cells, without reverting the growth arrest." (PMID 29990503, 2018).